MAT2A (methionine adenosyltransferase 2A)
Diseases named in the same sentence as MAT2A in open-access papers (continued):
Sharing a sentence is not in itself a finding about the gene and the disease.
cancer (continued). "A unique mechanism, associated with the accumulation of MTA, which is not degraded by MTAP, sensitizes cancer cells to PRMT5 and MAT2A inhibitors." (PMID 41465382, 2025). "Unlike MAT2A and MAT2B, which are strongly related to HCC, EEF2K is increased in many cancers, including HCC, allowing tumor growth and resisting cell death." (PMID 24098708, 2013).
tumor (70 papers, 2013 to 2026). "A low C/N of MAT2A expression in the tumorous tissues was found to be significantly associated with poorer survival in females (p = 0.004) but not in males with LIHC." (PMID 37240447, 2023). "OnB demonstrate their capacity to effectively reprogram crucial genes associated with hypoxia and tumor suppression, such as MAT2A and PDK-1." (PMID 38063756, 2023). "It is inversely correlated with STARD13, ZNF132 and MAT2A, which are implicated in tumor development." (PMID 34797887, 2021). "In hepatocytes, increased MAT2A expression is associated with malignant degeneration and uncontrolled tumor growth." (PMID 26418898, 2016). "Higher C/N ratio of MAT2A in the tumorous tissues was associated with poorer survival (p = 0.004)." (PMID 34065390, 2021). "Besides, we also found that liver-specific knockout of Mat2a causes expression changes of various genes that involved in tumor development, although the underlying mechanism still remains unclear." (PMID 35729157, 2022). "In tumours with loss of methylthioadenosine phosphorylase (MTAP), inhibition of methionine adenosyltransferase 2α (MAT2A) or protein arginine methyltransferase 5 (PRMT5) also induces a synthetic lethal effect." (PMID 41537447, 2026). "Following this line, the joined inhibition of MTAP and MAT2A promotes lethality in tumor models of CRC by reducing SAMe availability and increasing MTA level, thus rising MTA/SAMe ratio and inhibiting PRMT5 activity." (PMID 39941901, 2025). "The Met cycle, comprising a series of metabolic reactions, is often hyperactivated in tumor cells due to the upregulation of methionine adenosyltransferase 2A (MAT2A)." (PMID 40535116, 2025). "Recent research indicates that MTAP-deleted tumor cells exhibit specific vulnerabilities to MAT2A inhibition." (PMID 39983717, 2025). "It makes tumor cells more susceptible to PRMT5- and MAT2A-inhibiting drugs as well as to pemetrexed (antifolate therapy)." (PMID 40227771, 2025). "The in vivo IHC staining proved that MAT2A inhibition or methionine diet restriction enhanced IKZF1 expression in tumor tissue." (PMID 39983717, 2025). "Inhibition of MAT2A reversed the tumor initiating capability of GBM tumor-spheres in preclinical studies." (PMID 40507361, 2025). "For instance, glutaminase or methionine adenosyltransferase 2A deletion in mouse models enhanced T cell–mediated tumor control." (PMID 40475762, 2025). "SAM produced by methionine metabolism promotes the malignant biological behavior of tumor cells and inhibits the differentiation and functional roles of immune cells, so targeting MAT2A is expected to be a promising target to promote gastric cancer therapy." (PMID 40018041, 2025). "Methionine metabolism restriction or inhibition of the key enzyme MAT2A has differential effects on PD-L1 expression across various tumor cells." (PMID 39983717, 2025). "Analysis of clinical data and RNA sequencing results from 668 patients from TCGA database revealed that PRMT5 and MAT2A expression was higher in tumor tissues than in normal tissues." (PMID 40450009, 2025). "Methionine adenosyltransferase 2a (MAT2A) is a crucial metabolic enzyme involved in methionine metabolism and tumor-related epigenetics." (PMID 39983717, 2025). "Methionine restriction or MAT2A inhibitor SCR6639 increases CD8A+ T cell infiltration in the tumor microenvironment, enhancing the efficacy of immune checkpoint therapy in MTAP-deleted osteosarcoma." (PMID 39983717, 2025). "Novel therapeutic approaches against MTAP-deleted tumours aim to target PRMT5 either directly or indirectly via inhibition of MAT2A enzymatic function." (PMID 38755480, 2024). "“Combined inhibition of MTAP and MAT2a mimics synthetic lethality in tumor models via PRMT5 inhibition” JBC submission, September 2023." (PMID 38000655, 2024). "MAT2A acted as a tumor-protective factor, protecting tumor cells from ferroptosis and promoting growth." (PMID 37533434, 2023).
tumor (continued). "MAT2A protein was found in both the nuclear (N) and cytoplasmic (C) fractions of the tumor and normal tissues." (PMID 37240447, 2023). "Inhibiting MAT2A and reducing SAM levels has been proposed to cause PRMT5 inhibition both by removing its substrate and, in the case of MTAP-negative tumours, by providing a greater opportunity for MTA binding." (PMID 37795443, 2023). "In this review, we examine the current understanding of therapeutic vulnerabilities intrinsic to MTAP-negative tumours, focusing on MAT2A and PRMT5, which are receiving increasing attention in clinical development." (PMID 37795443, 2023). "In vivo models have shown that MAT2a knockdown reduced the growth and development of MTAP deficient tumor cells." (PMID 35747993, 2023). "In tumor-initiating cells, exogenous methionine is consumed at extreme rates, leading to pro-tumorigenic epigenetic modifications through methionine adenosyltransferase 2A (MAT2A), which metabolizes methionine to SAM to promote histone methylation." (PMID 37842241, 2023). "Tumor tissues had elevated MAT2A protein expression in both cytoplasm and nucleus compared to their adjacent normal tissues." (PMID 37240447, 2023). "Consistently, the tumour growth was strongly inhibited by SIRT4 overexpression but increased in the mice injected with MAT2A-E111A mutant." (PMID 36371321, 2022). "Cellular treatment with FIDAS-5, an inhibitor of MAT2A, strongly affected MAT2A activity and its related histone methylation, as well as cell proliferation and tumour growth, similar to that observed in cells stably overexpressing SIRT4." (PMID 36371321, 2022). "For example, methionine adenosyltransferase II alpha (MAT2A) increases the level of S-adenosylmethionine (SAM) in macrophages, and SAM promotes tumor-associated macrophage polarization through histone methylation." (PMID 35454171, 2022). "Loss of SIRT4 activates MAT2A, thereby increasing SAM level and dynamically regulating gene expression, which triggers the high proliferation rate of tumour cells." (PMID 36371321, 2022). "In contrast, MAT2A protein were found in both nuclear (N) and cytoplasmic (C) fractions of the tumor and normal tissues." (PMID 34065390, 2021). "Metabolomics and metabolite tracing analyses revealed that tumor-initiating cells in the lung have highly elevated methionine cycle activity and transmethylation rates that are driven by MAT2A." (PMID 34065390, 2021). "Among the most significantly downregulated targets were MAT2A and the tumor suppressive genes STARD13 and ZNF132." (PMID 34797887, 2021). "The correlation of higher MAT2A expression with poorer survival was somewhat contradictory to the lower MAT2A mRNA expression pattern in the tumor tissues, hence we further aimed to investigate the role of MAT2A protein in more depth." (PMID 34065390, 2021). "Some tumor-initiating cells show a tendency for increased activity of enzymes involved in the methionine metabolism, MAT2A, the enzyme required to covert methionine to SAM under ATP consumption, is one of them." (PMID 33572567, 2021). "Circ_0044516 and MAT2A levels were reduced in circ_0044516 siRNA-transfected tumor tissues, whereas miR-136 was increased." (PMID 34258296, 2021). "The findings indicated that the tumor suppressor activity of miR-203 is mediated by MAT2A and MAT2B downregulation and highlighted an oncogenic activity of MAT2B, linked to AKT activation." (PMID 34209866, 2021). "The tumor suppressor activity of miR-203 in HCC was proposed to be partially dependent on its inhibition of MAT2A and MAT2B." (PMID 34065390, 2021). "In HCC, miR-203 expression levels were inversely correlated with tumor cell proliferation, aggressiveness markers, and extent of MAT2A and MAT2B expression." (PMID 34209866, 2021). "This tumor had the lowest Mat1a/Mat2a ratio among the tested murine HCCs, and thus was expected to have the most aberrant DNA methylation." (PMID 25918251, 2015).
tumor (continued). "Overall, our results demonstrate that miR-21-3p functions as a tumor suppressor by directly targeting both MAT2A and MAT2B, indicating its therapeutic potential in HCC." (PMID 24098708, 2013). "Therefore, inhibiting MAT2A can serve as a potential therapeutic approach to suppress tumor growth, especially in cancers that lack MTAP." (PMID 40450009, 2025). "Therefore, targeting MAT2A is a potential therapeutic strategy to suppress tumor growth by diminishing SAM recovery." (PMID 40590219, 2025). "The expression of MAT2A increased in tumor cells with SAM insufficiency." (PMID 40299656, 2025). "However, while the antitumor effect of various MAT2A inhibitors is well documented, there is currently a paucity of studies on the impact of this new class of drugs on non-tumour, healthy cells." (PMID 38755480, 2024). "The LIHC tumor specimens presented aberrantly high MAT2A expression in both cytoplasm and nuclei." (PMID 37240447, 2023). "Importantly, short-term inhibition of the methionine cycle or exposure to the MAT2A inhibitor is sufficient to cripple the tumor-initiating capability of GBM tumorsphere cells." (PMID 39872059, 2023). "Since hypoxia supports the maintenance of GSCs, and GSCs have been found to exhibit a remarkable dependency on exogenous methionine, we then explored whether adherent tumor cells under hypoxia had a similar enhanced MAT2A expression as in GSCs." (PMID 39872059, 2023). "MAT2A activity is required to support protein synthesis and tumour growth." (PMID 36792800, 2023). "Furthermore, a notable negative correlation emerges between the expression levels of PDK-1 and MAT2A and both tumor size and metastasis." (PMID 38063756, 2023). "Surprisingly, the results showed that MAT2A expression was down-regulated in adherent tumor cells under hypoxia, indicating that the enhanced expression of MAT2A by hypoxia might be present only in GSCs." (PMID 39872059, 2023). "Moreover, inhibiting tumor methionine metabolism by MAT2A knockout protected tumor-infiltrating CD8+ T cells from exhaustion in a syngeneic mouse tumor model." (PMID 36033438, 2022). "Induction of MAT2A/MAT2B favors tumor growth and survival and also enhances tumor migration." (PMID 34065390, 2021). "Indeed, transient pharmacological inhibition of the methionine cycle at the level of MAT2A seems to efficiently block tumor-initiation." (PMID 33572567, 2021). "In conclusion, our results demonstrate, for the first time, that the tumor suppressor miR-203 targets the 3’-UTRs of MAT2A and MAT2B and inhibits their expression, and show that miR-203 expression is genetically regulated and strongly contributes to determine patients’ outcome." (PMID 31073374, 2019). "Moreover, the expression level of PDK-1 and MAT2A was found to be negatively correlated with the tumor size and metastasis." (PMID 28839175, 2017). "So, MAT2A has a potential effect on tumor development and progression." (PMID 24636201, 2014). "Thus, the oncogenic expression of c-MYC downstream of the mTORC1 pathway could play a role in tumor cell reprogramming to dietary methionine sources through promoting the transcription of MAT2A." (PMID 40299656, 2025). "Inhibiting MAT2A further depletes SAM, exacerbating PRMT5 suppression and selectively impairing tumor cell proliferation while sparing normal tissues." (PMID 40430308, 2025). "Alterations in enzymes and cofactors—including MAT2A, SAM, and α-ketoglutarate—not only affect DNA and histone methylation but also shape the tumor’s adaptive landscape in the face of therapy." (PMID 40874022, 2025). "MAT2A indirectly enhances the methylation of PRMT5 by promoting the production of SAM, which is closely related to the tumor progression of liver cancer and colorectal cancer." (PMID 40240755, 2025). "Preclinical studies show anti-tumor activity of these agents and reduced SAM levels upon MAT2A inhibition." (PMID 41439984, 2025).
tumor (continued). "In HCC, the expression level of MAT2A is greater than that of MAT1A, leading to lower SAM production and rapid tumor growth." (PMID 37781509, 2023). "In MTAP null tumors, inhibition of Met adenosine transferase 2A (MAT2A) inhibits Met synthesis of SAM, thereby inhibiting tumor growth." (PMID 37699892, 2023). "We demonstrated that limiting methionine intake or targeting MAT2A efficiently suppresses the tumorigenicity of GBM tumorsphere cells, thus present a novel perspective on hypoxia-mediated maintenance of tumor-initiating cells." (PMID 39872059, 2023). "Over-expression of MAT2A in LIHC was proposed to be a useful biomarker for predicting and monitoring tumor recurrence, especially early after hepatic resection." (PMID 37240447, 2023). "AG-270 is an orally active inhibitor of MAT2A, which dose-dependently reduced SAM levels in tumor and blocked tumor growth in a pancreatic xenograft model." (PMID 34981784, 2022). "Results showed that both MAT2A and PDCD6 displayed an upregulated expression in tumor tissues compared with both normal tissue and adjacent normal tissues." (PMID 35396512, 2022). "In human colorectal cancer cell lines, inhibition of MAT2A and MAT2B by SAM or miR-34a/b expression inhibited tumor migration and invasion in vitro." (PMID 34065390, 2021). "MAT1A/MAT2A switch has been involved in RAS/ERK, IKK/NF-kB, PI3K/AKT, and NF-kB signaling up-regulation, leading to increase in tumor cell proliferation, cell survival, and micro-vascularization." (PMID 31073374, 2019). "We found that the L1CAM, TSPAN3 and SERPINA3 gene expression were significantly up-regulated in M than Wt sporadic tumor samples, whereas COL1A1 and MAT2A mRNA showed similar levels in both groups." (PMID 28418912, 2017). "In this section, we will explore the different therapeutic targets identified over time, beginning with the recently discovered PRMT5/methionine adenosyltransferase 2A (MAT2A) axis and then tracing back to earlier targets that have shaped our understanding of MTAP-deleted tumor vulnerabilities." (PMID 41439984, 2025). "We also found that NPC268 consistently harbors CN losses in three chromosomal arms in both tumor and cell line, including the 9p21.3 co-deletion of CDKN2A and MTAP which is a common event in NPC, implying that NPC268 could be vulnerable to MAT2A inhibitors." (PMID 38358347, 2024). "Notably, in HCC, the expression of MAT2A is more dominant than that of MAT1A, thereby leading to decreased SAM production and rapid tumor growth." (PMID 37781509, 2023). "Importantly, pharmacological inhibition of the methionine cycle or methionine adenosyltransferase II alpha (MAT2A) reduces protein synthesis rate and tumor cell growth." (PMID 39872059, 2023). "Tumor and plasma levels of SAM, a product of the MAT2A-catalyzed reaction of methionine and ATP, were used as biomarkers of AG-270 target engagement in mouse xenografts and a first-in-human trial, respectively, providing guidance for dose selection in future clinical studies." (PMID 34981784, 2022). "Quantitative analyses revealed that high folate-feeding significantly increased the ratio of liver/body weight and maximum tumor size in liver in Mat2a WT but not KO mice." (PMID 35729157, 2022). "MAT2A is a transcriptional corepressor for HO-1 expression by supplying SAM for methyltransferases, which may be one of potential mechanism of MAT2A as tumor suppressor in kidney carcinogenesis." (PMID 24636201, 2014). "Methionine starvation and backfill experiments demonstrated that tumor-initiating cells are dependent on methionine metabolism, and its main product, SAM, is the source of nucleic acid methylation and histone methylation methyl group, which is catalyzed by Methionine adenosyltransferase IIA(MAT2A)." (PMID 40018041, 2025).
tumor (continued). "Here we have reviewed current pharmacological methods of targeting SAM production via MAT2A inhibition and direct PRMT5 inhibition (both of which reduce PRMT5-specific methylation reactions) and reported evidence for and against the selectivity of these treatments for MTAP-negative tumours." (PMID 37795443, 2023). "Furthermore, MAT2A was reported to act as a transcriptional corepressor for heme oxygenase-1 (HO-1) expression by supplying SAM for methyltransferases, thus it was suggested to act as a tumor suppressor in kidney carcinogenesis." (PMID 34065390, 2021). "Furthermore, miR-203 transfection induced an increase in the SAM content of transfected cells, probably dependent on the reduction of MAT1A/MAT2A switch, the latter being largely responsible for SAM levels restriction and increase in proliferation capacity of tumor cells." (PMID 31073374, 2019). "The underlying mechanism is by MTDIA causing accumulation of MTA in tissues regardless of tumor MTAP genotype due to the loss of MTA catabolism in all cells, thereby enhancing the MTA:SAM ratio, inhibiting PRMT5 activity, and providing dose-dependent sensitivity to MAT2a inhibitors." (PMID 38000655, 2024). "On the other hand, there was no statistical significance found in MAT2A between the adjacent normal and the HCC tumor tissues." (PMID 35008908, 2022).
infection (5 papers, 2008 to 2025). The state of being infected such as from the introduction of a foreign agent such as serum, vaccine, antigenic substance or organism. "Meanwhile, the infection increased the mRNA transcription of MAT2A, AMD1, SMS, and AHCY mRNA with the same MOI." (PMID 38130504, 2024).
hematological diseases (1 paper, 2020). "Interestingly, upon MAT2A inhibition, we detected the cholesterol efflux transporters ABCG1 and ABCA1 of the cholesterol metabolism to be significantly upregulated, resulting in known anti-proliferative and apoptotic effects in hematological diseases." (PMID 32456310, 2020).
kidney disease (1 paper, 2025). "Most prominent and consistent in our dataset and across published datasets from patients, expression of the gene encoding the SAM synthetase, Mat2a, was decreased in injured PTCs that emerge during the course of kidney disease triggered by metabolic stress (e.g., HFD) compared with other PTCs." (PMID 41031893, 2025).
metabolic disorder (1 paper, 2013). "Mammals encode a liver-specific isoenzyme, MAT1A, that is genetically linked with an inborn metabolic disorder of hypermethioninaemia, as well as a ubiquitously expressed isoenzyme, MAT2A, whose enzymatic activity is regulated by an associated subunit MAT2B." (PMID 23425511, 2013).
MAT2A also shares sentences with these, for which no sentence is quoted: colon adenocarcinoma (2 papers); COVID-19 (2); nasopharyngeal carcinoma (2); thoracic aortic aneurysm (2); acute lymphoblastic leukemia (1); acute myeloid leukemia (1); adenocarcinoma (1); alcoholic hepatitis (1); bladder urothelial carcinoma (1); brain cancer (1); cervical squamous cell carcinoma (1); Chagas disease (1); chronic hepatitis (1); CNS tumors (1); cryptococcosis (1); dependence (1); diabetes (1); endometrial cancer (1); Ewing sarcoma (1); fibrosarcoma (1); Glucose intolerance (1); head and neck squamous cell carcinoma (1); Hepatitis (1); hepatoblastoma (1); inflammatory bowel disease (1); iron deficiency (1); kidney (1); kidney chromophobe (1); monoclonal gammopathy of undetermined significance (1); neuroblastoma (1).
A further 15 diseases each share a sentence with MAT2A in 1 paper.